SNORD114-7 (small nucleolar RNA, C/D box 114-7)
Synonyms: 14q(II-7)
Gene: Small nucleolar RNA gene on chromosome 14 (100,963,054 to 100,963,130, forward strand). Ensembl gene ENSG00000199390.
Gene Ontology:
Biological process: RNA processing
Cellular component: nucleolus
Homologues: Orthologues: chimpanzee SNORD114-7 (100% identical), macaque SNORD114-7 (96% identical). Paralogues in human: SNORD114-4 (68% identical), SNORD114-31 (66% identical), SNORD114-15 (65% identical), SNORD114-24 (65% identical), SNORD114-3 (65% identical), SNORD114-9 (65% identical), SNORD114-1 (64% identical), SNORD114-12 (64% identical), SNORD114-21 (64% identical), SNORD114-23 (64% identical), SNORD114-26 (64% identical), SNORD114-10 (62% identical), and 26 more.